CD4 (CD4 molecule)
Diseases named in the same sentence as CD4 in open-access papers (continued):
Sharing a sentence is not in itself a finding about the gene and the disease.
tumor (continued). "To get insight into the direction of changes in the frequency of CD4+Teff and Treg TILs expressing common TCRs, which may accompany tumor regression, we analyzed the abundance of such clones in untreated and DTA-1 treated mice." (PMID 28638937, 2017). "CD4+ T cells proliferating in response to inoculated tumor may include antigen-specific as well as “bystander-activated” clones." (PMID 28638937, 2017). "These long-lasting anti-tumor effects are mediated by CD4+ and CD8+ T cells." (PMID 28855903, 2017). "Interestingly, CD137 was elevated on CD4+ T cells that had been primed in vivo by irradiated tumor cells and Surek together with HB304." (PMID 27966460, 2017). "This prolonged condition also generates an immuno-suppressive environment by recruiting suppressor cells, including CD4+CD25+Foxp3+ regulatory T cells (Treg), myeloid-derived suppressor cells (MDSCs), tumor-associated macrophages (TAMs), N2-polarized neutrophils, and regulatory/tolerogenic DCs." (PMID 28212561, 2017). "Interestingly, added frequencies of individual tumor-reactive TCRs in pLN, dLN, and TILs amounted to 22–34% of all CD4+Teff clones, but only to 5–13% of Treg clones in respective anatomical locations." (PMID 28638937, 2017). "The current study found that lymphodepletion and the transfer of ex vivo—expanded CD4+ T cells could induce polyclonal tumor-specific T cells." (PMID 28854279, 2017). "A broad repertoire of TCR Vβ on CD4+ tumor-specific T cells was observed." (PMID 28854279, 2017). "However, in several tumor models, CD4+ T cells can induce killing of apparently MHC II-negative (MHC IINEG) cancer cells." (PMID 27626487, 2016). "Additionally, lower intensity TNFR2 expression was observed for tumor-infiltrating CD4+Foxp3− and CD8+ Teff cells, and for PBMC-derived Teff cells following in vitro stimulation with PHA-P/IL-2 or specific cognate antigenic peptide." (PMID 27626702, 2016). "Moreover, inactivation of CD4+CD25+Foxp3+ Tregs by an anti-CD25 antibody following DC-tumor FC vaccination significantly improves antitumor immunity in a murine model." (PMID 27240347, 2016). "Similarly, tumor antigen specific CD4+ Th1 cells attracted to the tumor microenvironment will secrete IL-2, TNF-α, and IFN-γ, creating an environment for enhanced activity of antigen presenting cells (APC)." (PMID 27766079, 2016). "Furthermore, blockade of Nrp-1 resulted in significantly augmented tumor-derived CD4+IL-17A+ (Th17) cells." (PMID 27075020, 2016). "Importantly, the effector and memory CD4+ T cells induced by DC-tumor FCs are crucial for the maintenance of long-term antitumor immunity." (PMID 27240347, 2016). "As a corollary, IL-2 administration in mice may stimulate CD4+ T cell proliferation in tumor-bearing mice, and it is well-known that the Th2 cells can provide help for B cell function." (PMID 27528023, 2016). "Both the increased Treg cell frequency and the MDSC-caused suppression of CD4+ T cell proliferation were only seen in tumor-bearing CSC mice but not in tumor-free CSC mice 9 days after cessation of CSC." (PMID 27391954, 2016). "SDF-1 attracts regulatory T cells (CD4+ subtype) into the tumor." (PMID 26985769, 2016). "The roles and mechanisms of tumor infiltrating effector CD4+ TILs are complex and still being defined, and therefore the intriguing finding of effector CD4+ T cells providing therapeutic efficacy in the absence of CD8+ T cells will be the subject of future work." (PMID 28018602, 2016). "In the absence of IL-10, impaired Treg-derived Nrp-1 suppressive functions and Foxp3 expression may be lost, allowing their transformation into effector CD4+ T cells to counteract tumor growth." (PMID 27075020, 2016). "Furthermore, Engineered CD19-specific CD4+ T cell responses comprised at least part of the anti-tumor effects against B-cell malignance in a few of the recent successful clinical trials." (PMID 26527725, 2016).
tumor (continued). "Therefore cancer immunotherapies that include targeting of CD4+ Th1-like cells are promising for inducing complete, durable anti-tumor rejection." (PMID 27588200, 2016). "In an in vivo study, the combined treatment of MMTV-PyMT mice with paclitaxel and anti-CSF1 antibody slowed primary tumor development, reduced development of high-grade carcinomas, and decreased pulmonary metastasis by 85% and increased CD4+ and CD8+ T-cell infiltration in primary tumors." (PMID 27756885, 2016). "Thus, increasing a BC patient's ability to mount an immune response with treatments such as DC vaccination will subsequently increase in CD8+ and CD4+ T cells in the tumor stroma, allowing for increase in pCR." (PMID 27766079, 2016). "In addition co-transfer of these CD4+ Th1-like cells with CD8+ CTL significantly enhanced tumor regression, leading to complete cure in 80% of mice bearing established B16-OVA." (PMID 27588200, 2016). "Interestingly, the non-irradiated tumours of mice treated with 15 Gy+L19-IL2 showed a significant (p < 0.01) increased percentage of CD4+ T cells compared to irradiated tumours." (PMID 27994647, 2016). "Furthermore, we have also shown that CD8+ CTL, but not CD4+ Th cells, comprise the main subset of T cells responsible for eliminating tumor cells; however, the presence of CD4+ Th1-like cells is necessary to enhance complete tumor regression." (PMID 27588200, 2016). "Subsequent analysis showed that at the time of euthanasia (when tumor size reached > 100mm2 or at day 120), the percentage of peripheral blood CD4+ T cells correlated with the CD4+ T cell proportions in the spleen and tumor-draining LN, and within the tumor itself in tumor-bearing mice." (PMID 27121060, 2016). "Alternatively, soluble signals derived from tumor B cells, (whose nature is still unknown), may allow the conversion of naive CD4+ T cells into Foxp3+ induced Tregs, similar to that reported for H. felis." (PMID 26657504, 2016). "The decline of IL-2 levels could be due, at least in part, to its consumption by antigen-induced IL-2α receptor+ (CD25+) cells, such as activated tumor-specific CD4- and CD8-T lymphocytes." (PMID 26973649, 2016). "Critically, NK cytotoxicity was clearly inhibited by TGF‐β and the expression of activating receptor NKp46 was downregulated in neoplastic lymph nodes, suggesting that inactivated NK cells enhance tumor formation during BLV‐infection by inducing TGF‐β secretion from CD4+CD25+ Foxp3+ T cells." (PMID 27042304, 2016). "Both these CD4+ T cell subsets facilitate a pro-tumor environment through the promotion and maintenance of an immunosuppressive and pro-tumor inflammation environment that could favor tumorigenesis, cancer progression and metastasis." (PMID 27784305, 2016). "Our in vivo studies showed that inhibition of tumor growth and prolonged mouse survival could be attributed to inhibition of aTreg cell recruitment resulting in expansion of tumor infiltrating CD4+ and CD8+ T cells." (PMID 27177223, 2016). "In contrast, both SCIB1 and the tumor induce similar avidity CD4 responses." (PMID 27825115, 2016). "Tumor growth remained inhibited in the anti-CD4 and rat IgG-treated groups." (PMID 27063435, 2016). "In addition to their effects on CD4+ T cells, B cells responding to tumor in the presence of T cell help secreted tumor-specific anti-HEL antibody, which we detected in the serum." (PMID 27121060, 2016). "A key observation was that vaccination even with minimalist antigens such as non-glycosylated 9mers produced CD8+ as well as CD4+ T-cell repertoires that recognized both non-glycosylated and glycosylated peptides as well as tumor-associated MUC1." (PMID 26788922, 2016). "Furthermore, whole tumor cell immunizations result in polyvalent stimulation of both CD4+ Th cells and CD8+ CTLs against a broad range of Ags." (PMID 26795730, 2016). "The triple combination induced profound CD8 and CD4 effector T cell infiltration in the tumor." (PMID 27330804, 2016).
tumor (continued). "Additionally, the fact that the antibody response is dominated by IgG can be considered as direct proof that CD4+ T cell-dependent responses are triggered upon tumour inoculation as immunoglobulin class switching occurred." (PMID 27427766, 2016). "Hence, we analyzed the splenocytes isolated from rNDV-treated tumor-bearing mice, and found that the percentage of CD4+ T and CD8+ T cells in rNDV-IL2-NP/P treated group were much higher than other rNDV-treated groups." (PMID 27736965, 2016). "Furthermore, fucoidan inhibited tumor cells migration and CD4+ T lymphocytes, especially Treg cells, recruitment induced by M2 macrophages conditioned medium through suppression of CCL22." (PMID 27775051, 2016). "FAS ligand expression on tumor cells could induce CD4 and CD8 T cell death and neutrophil apoptosis for immune escape." (PMID 27259252, 2016). "To date, knowledge of the mechanistic basis of anti-tumor CD4+ T cell responses is limited." (PMID 27626487, 2016). "In this regard, we verified whether tumour lysate loaded-DCs could facilitate the clonal expansion of Treg cells (CD4+CD25+ regulatory T-cells) in vivo." (PMID 26795765, 2016). "Moreover, we compared distribution of CD4+ T& CD8+ T cells in the tumor tissues in different groups." (PMID 27669687, 2016). "In this fashion, insufficient CD4+ Th1 cell response may facilitate the natural progression of tumor cells." (PMID 27766079, 2016). "Therefore, the fusion of DCs and immunogenic whole tumor cells activates antigen-specific CD4+ and CD8+ T cells that produce high levels of IFN-γ." (PMID 27240347, 2016). "EG7 tumor was inhibited or eradicated with an antibody against CD4 expressed by these cells." (PMID 27572622, 2016). "Interestingly, there were significantly increased numbers of CD4+IFN-γ+ Th1 cells in the tumor, spleen and TDLN harvested from the IL-10−/− B16/F10 mice." (PMID 27075020, 2016). "To assess whether tumour-resident DCs influence the activity of Ag-experienced T cells, we co-cultured TADCs from LLC-OVA tumours with sorted CD4+ or CD8+ T cells from the tdLNs of 12-day-old LLC-OVA-bearing mice." (PMID 28008905, 2016). "Collectively these data support a role for aberrant HLA-DR/MHC-II expressing tumours as being a uniquely immunogenic subtype (with the ability to stimulate CD4(+) T-helper cells) which may adapt by expressing PD-L1." (PMID 26822383, 2016). "In mice, CD4+ T cells were shown to be required for improved tumor elimination by CD8+ T cells." (PMID 26980946, 2016). "CD4+CD25+ regulatory T (Treg) cells suppress tumor immunity by inhibiting immune cells." (PMID 27887569, 2016). "Here we developed a novel pre-clinical model in which the effects of tumor-specific CD4+ T cells, B cells and antibodies could be studied under controlled conditions in a well-defined transgenic system." (PMID 27121060, 2016). "T-VEC may support immunotherapy by enhanced by IFNγ and TNFα production, which can increase PD-L1 expression, promote influx of effector CD8+ T cell to the tumor microenvironment and decrease the number of CD4 + FoxP3+ regulatory T cells." (PMID 27660707, 2016). "It is possible that combinatorial treatment regimens may induce changes that facilitate or enhance MHC II display on tumor cells, thereby enabling direct CD4+ T cell cytotoxicity." (PMID 27626487, 2016). "Interestingly, in the case of CD4+ OT-II T-cells, the highest proliferation was measured when T cells were co-cultured with tumour-derived cDC2s." (PMID 28008905, 2016). "Further, chemokine-fusion vaccine therapy significantly reduces tumor burden, slows tumor growth, and enhances mouse overall survival compared to antigen-only, irrelevant-antigen, and mock vaccines, with efficacy mediated by both CD4+ and CD8+ effector T cells." (PMID 28018602, 2016). "Accordingly, the hypothesis of our group is that high concentrations of IL-2 activate immune system cells, such as CD8, CD4 and γδ T cells, and NK cells, to favour the elimination of tumour cells." (PMID 27293315, 2016).
tumor (continued). "However, RCC can also suppress the anti-tumor immunity of naïve and memory CD4+ T, natural killer (NK), and dendritic cells, and evade the cytotoxic effect of NK cells." (PMID 26772545, 2016). "CD4+ T lymphocytes are central to immune system functions and play a vital role in tumor immunity." (PMID 27368058, 2016). "As illustrated by the present findings, CD4+ T cells may trigger cell signaling programs and release of cytokines and other factors that alter the tumor microenvironment." (PMID 27626487, 2016). "Furthermore, a recent study showed that a MHC class II-binding peptide, HLA-G26–40, was effective in eliciting a tumor-reactive CD4+ T cell response." (PMID 27999823, 2016). "Thus, the percentages of activated T cells and CD4-Tregs in peripheral blood samples were positively correlated with those in tumor samples from these NSCLC patients." (PMID 27689405, 2016). "Furthermore, our data suggest that Nrp-1-derived Tregs appear to be quite different from CD4+Nrp1+ T cells and that these cells most likely play different roles in anti-tumor responses." (PMID 27075020, 2016). "CD4+ T helper cells exhibit a profound effect in initiating and maintaining anti-tumor immunity: secretion of Th1 cytokines such as IL-2 and IFN-γ promote CD8+ cytotoxic and natural killer cell function, as well as induction of MHC class II molecule expression on tumor cells." (PMID 27766079, 2016). "However, its application using specific peptides is limited to patients expressing tumor-associated MHC class I restricted peptides that fail to elicit MHC class II and CD40L-mediated CD4+ T cell helper responses." (PMID 26795730, 2016). "However, the number of CD4+ cells in the Tumor group was higher than the Treatment group and were located around the tumor cells." (PMID 27669687, 2016). "However, recent studies suggest that IFN-γ and other cytokines produced by CD4+ Th1 T-cells also targets tumor cells directly in vivo by inducing cellular senescence thereby keeping tumors in check, which is consistent with our findings." (PMID 26701207, 2016). "In particular, macrophages exposed to TGFβ1 have been shown to acquire an M2-like phenotype characterized by a number of tumor-promoting functions, including the ability to promote angiogenic activity, suppress T cell proliferation and induce CD4+ FOXP3+ Treg differentiation." (PMID 27589814, 2016). "In addition, Se-CEPS improved the proportions of CD8+ and CD4+ T lymphocytes in the spleen, thereby inhibiting tumor growth." (PMID 27347005, 2016). "We found that all those IRs were increased in the CD4+ or CD8+ T cells in tumor-bearing mice." (PMID 27447564, 2016). "In this context, it would be of interest to investigate whether the induction of auto-Abs to immature ADAM10 might reflect the activation of specific CD4+T helper cells able to foster an active anti-tumor response." (PMID 27517630, 2016). "Up to now, Foxp3 expression has been found only in CD4+ T cells and in some tumor cell lines." (PMID 27350539, 2016). "Thus our model mimics a common situation in which tumor antigen-specific CD4+ T cells are unable to directly recognize an MHCII-negative tumor." (PMID 27121060, 2016). "The observation describes that B cells may attenuate anti-tumor cytotoxic T cells responses and potentiate the local expansion of CD4+FoxP3+ Tregs in murine tumor environment." (PMID 27331871, 2016). "There was little change of CD4 marker in the tumor tissue in responses to either monotherapy." (PMID 26956047, 2016). "However, mice fed the KD had a significant increase in the percentage of CD4+ T cells infiltrating the tumor in comparison to SD." (PMID 27178315, 2016). "Moreover, CD4+CD25+Foxp3+Tregs are considered as suppressors in immune surveillance and anti-tumor immunity, which are also proved associated with HCC invasiveness." (PMID 27439521, 2016). "Th17 cells, another subset of CD4+ cells, play dynamic role in the tumor microenvironment." (PMID 27120805, 2016).
tumor (continued). "While T cells (all tumor-infiltrating L-selectin+ T cells, comprised of both naive and central memory CD4+ and CD8+ cells) are localized to TLO, overall T cell infiltrate and density appears to play a minor role in patient outcome when evaluated independently of other prognostic markers." (PMID 27555845, 2016). "CD4+ T cells with a Th1 phenotype that are capable of producing multiple Th1 cytokines are well known to be important for enhancing CD8+ CTL responses during an anti-tumor immunity." (PMID 27588200, 2016). "However, Tregs from spleens of mice with actively growing tumor were more potent suppressor cells than those from spleens with dormant tumor cells i. e. they inhibited the proliferation of CD4+ T cells at the lowest ratio (0.25:1)." (PMID 27959896, 2016). "In addition, CD8+, CD4+ and B cell infiltrates were detected in recurrent tumor tissue obtained from patients following progression on-study." (PMID 27576783, 2016). "The absolute number of induced FoxP3+ regulatory T cells (iTregs) within the tumor-specific CD4+ T cell compartment was unaffected by the presence of B cells, although the B cell-dependent reduction in absolute numbers of CD4+ T cells caused iTregs to represent a higher proportion of CD4+ T cells." (PMID 27121060, 2016). "Moreover, mice with more than 20 human CD4+ T cells/μL or 2 CD8+ T cells/μL of peripheral blood presented significantly higher tumor regression than others." (PMID 27409425, 2016). "We suppose these peculiar CD4+, CD56+, EBER+ tumors of the small intestine may represent a special variant of ENKTCL or even novel entity due to their unique clinical and pathological features." (PMID 27564014, 2016). "This insight may guide the selection of antigen targets and choice of conditioning regimen in immunotherapeutic interventions utilizing tumor-specific CD4+ T cells." (PMID 27626487, 2016). "The levels of CD4+Foxp3+ cells had a negative impact on adoptive immunotherapy and immune responses that is consistent with the increased anti-tumor effect of CAR-T with deleted lck domain of CD28 linked to IL-2 production." (PMID 26999211, 2016). "Additionally, Treg depletion followed by cancer antigen vaccination generated effective anti-tumor CD4+ and CD8+ T-cell responses in metastatic breast cancer patients." (PMID 27509527, 2016). "However, a significant increase in the frequency of IL-17+TNF-α+ CD4+ T cells was observed in tumor tissue relative to adjacent uninvolved intestine (p < 0.05)." (PMID 27014625, 2016). "We then analyzed the expression profile of CD4 subtypes, commonly modulated in tumor." (PMID 27120805, 2016). "Although HLA-DR and CD4+ infiltrate are biologically connected, association of HLA-DR with CD8 infiltrate may be suggestive evidence that enhanced CD4+ Th infiltrate could support the continued accumulation of CD8+ CTLs in the tumour microenvironment." (PMID 26822383, 2016). "Indeed, CD4 T cells in MSI tumors have been found to secret high amounts of pro-inflammatory cytokines which positively influenced the anti-tumor response." (PMID 27060000, 2016). "Subsequent data has shown the inclusion of tumor reactive CD4 T cells in ACT could enhance persistence of transferred CD8 T cells." (PMID 27472363, 2016). "Thus, following either tumour challenge or peptide immunization, B cells were required for the full clonotypic diversity of the CD4+ T-cell response." (PMID 26728651, 2016). "Similar anti-tumor efficacy could be achieved by giving a combination of 2.5 × 106 CD4+ Th cells and CD8+ CTL." (PMID 27588200, 2016). "Therefore, given in combination with checkpoint inhibitors, DC vaccination provides a synergistic promotion of Th1 response and increases the frequency of tumor infiltrating CD4+ and CD8+ T cells, ultimately providing an improved prognosis." (PMID 27766079, 2016). "It was found that CTLA-4 blockade therapy could greatly reduce the percentages of Tregs (CD3+CD4+Foxp3+) in secondary tumours." (PMID 27767031, 2016).